CYTH3 (cytohesin 3)
Description:
Promotes guanine-nucleotide exchange on ARF1 and ARF6. Promotes the activation of ARF factors through replacement of GDP with GTP. Plays a role in the epithelial polarization (By similarity).
Synonyms: Grp1; ARNO3; PSCD3; cytohesin-3
Tractability: Small molecule: a structure with a bound ligand is known. Antibody: its Gene Ontology location is reachable by antibodies, with high confidence; UniProt places it where antibodies can reach, with medium confidence. PROTAC: ubiquitination databases record sites on it; its protein half-life has been measured.
Chemical probes: SecinH3
Gene: Protein-coding gene on chromosome 7 (6,161,776 to 6,272,650, reverse strand). Ensembl gene ENSG00000008256.
Subcellular location: Cytoplasm, cytosol; Cell membrane; Cell junction, adherens junction; Cell junction, tight junction
Subcellular location (Human Protein Atlas): Cytosol; Nucleoplasm
Pathways (Reactome):
Vesicle-mediated transport: Intra-Golgi traffic
Gene Ontology:
Molecular function: guanyl-nucleotide exchange factor activity; phosphatidylinositol-3,4,5-trisphosphate binding; protein binding
Biological process: Golgi vesicle transport; establishment of epithelial cell polarity; regulation of ARF protein signal transduction
Cellular component: cytosol; plasma membrane; adherens junction; bicellular tight junction; Golgi membrane; cytoplasm; ruffle
Genetic constraint (gnomAD): Loss-of-function variants: 17 observed, 46.3 expected, observed/expected ratio (o/e) 0.37, 90% interval 0.25 to 0.55. The synonymous counts are far from expectation, so gnomAD's model fits this gene poorly and the ratio says little. Missense variants: 383 observed, 488.45 expected, observed/expected ratio (o/e) 0.78, 90% interval 0.72 to 0.85. Synonymous variants: 238 observed, 186.34 expected, observed/expected ratio (o/e) 1.28, 90% interval 1.15 to 1.42.
Homologues: Orthologues: chimpanzee CYTH3 (100% identical), guinea pig CYTH3 (99% identical), mouse Cyth3 (99% identical), pig CYTH3 (98% identical), rat Cyth3 (97% identical), dog CYTH3 (96% identical), tropical clawed frog cyth3 (94% identical), macaque CYTH3 (92% identical), zebrafish cyth3b (91% identical), zebrafish cyth3a (88% identical), Drosophila melanogaster Sec71 (40% identical), Caenorhabditis elegans agef-1 (34% identical), and 5 more. Paralogues in human: CYTH1 (83% identical), CYTH2 (79% identical), CYTH4 (71% identical), ARFGEF2 (44% identical), ARFGEF1 (44% identical), GBF1 (37% identical), IQSEC1 (34% identical), IQSEC2 (31% identical), IQSEC3 (31% identical), PSD3 (26% identical), PSD (25% identical), MON2 (25% identical), and 3 more.
Diseases named in the same sentence as CYTH3 in open-access papers:
CYTH3 is named in the same sentence as 22 diseases in open-access papers, as found by Europe PMC text mining. Sharing a sentence is not in itself a finding about the gene and the disease. The quoted sentences say what the papers report.
hepatocellular carcinoma (1 paper, 2021). A malignant tumor that arises from hepatocytes. "CYTH3 is involved in the control of Golgi structure and function, and its upregulation in hepatocellular carcinoma is associated with poor survival." (PMID 34413360, 2021).
intrauterine growth restriction (1 paper, 2012). "An unexpected finding from this paper was the decrease in expression of myometrial ARF6/CYTH3 and ARF6-GTP levels in pregnancies complicated by pre-eclampsia, intrauterine growth restriction or haemorrhage." (PMID 22666423, 2012).
liver cancer (1 paper, 2016). An epithelial or non-epithelial malignant neoplasm that arises from the liver. "Two of these genes (TSPAN9, CYTH3) were directly correlated with cancer, with CYTH3 identified as a biomarker in liver cancer." (PMID 27478834, 2016).
ovarian carcinoma (1 paper, 2021). A malignant neoplasm originating from the surface ovarian epithelium. "The roles of CYTH3 and ERI1 in ovarian cancer tumorigenesis have yet to be extensively explored in the literature." (PMID 34413360, 2021). "In addition to traditional pathological factors (such as nodal stage, presence of metastasis and tumour grade), determining the presence of molecular markers (CYTH3 and S100A14) may allow us to more adequately assess a patient’s risk of developing chemoresistance in ovarian cancer." (PMID 34413360, 2021).
cancer (6 papers, 2016 to 2025). A tumor composed of atypical neoplastic, often pleomorphic cells that invade other tissues. "Then, risk scores were calculated for every cancer sample calculated by using the following formula: Riskraw = DAD1*2.316+CYCS*1.426+CSNK2A2*1.576+VPS25*0.728+VDAC1*0.976+TMLHE*0.381+CYTH3*0.024+PRKCA*0.260-TP73*0.567+FZD6*0.047+SQSTM1*0.094-MAP2K7*3.070." (PMID 35185897, 2022). "Using the Genomics of Drug Sensitivity in Cancer (GDSC) and The Cancer Genome Atlas (TCGA) databases, we identified 4 biomarkers (CYTH3, GALNT3, S100A14, and ERI1) to predict cisplatin sensitivity." (PMID 34676288, 2021). "Similarly, low expressions of CYTH3, NOVA1, and EPHA6 were highly correlated with longer OS in patients with other types of cancers." (PMID 36506313, 2022).
CYTH3 also shares sentences with these, for which no sentence is quoted: tumor (3 papers); breast carcinoma (1); diabetes (1); gallstones (1); heart failure (1); infection (1); Insulin resistance (1); left ventricular hypertrophy (1); liver fibrosis (1); metabolic disease (1); neurodegenerative disease (1); Obesity (1); osteosarcoma (1); pancreatic disease (1); prostate carcinoma (1); type 2 diabetes (1); viral infection (1).